CDK5 (cyclin dependent kinase 5)
Diseases named in the same sentence as CDK5 in open-access papers (continued):
Sharing a sentence is not in itself a finding about the gene and the disease.
cancer (169 papers, 2010 to 2026). A tumor composed of atypical neoplastic, often pleomorphic cells that invade other tissues. "Nevertheless, given that aberrant DNA methylation is a hallmark of cancer, Cdk5 stands as a plausible candidate for the upstream regulator of this fundamental epigenetic process." (PMID 41369365, 2025). "CDK5 deregulation is causatively linked to several diseases, including cancer, senescence, diabetes, immune dysfunction and inflammation." (PMID 37993880, 2023). "Cyclin-dependent kinase 5 has been associated with cancer development and cyclin-dependent kinase 5 inhibitors block the growth of tumors in distinct models of MTC but has yet to be explored in clinical trials." (PMID 37204852, 2023). "Cdk5 regulates neuronal functions but is also associated with cancer development and has been considered a potential target for cancer treatment." (PMID 36829834, 2023). "A few studies have indeed shown that hyperactivation of CDK5 by inducing p25 formation causes apoptosis in cancer." (PMID 37993880, 2023). "Metastasis is a key feature in cancer progression, and the activity of CDK5 was found to be associated with invasive phenotype, such as cytoskeleton remodeling." (PMID 35006426, 2021). "The association of CDK5 inhibitors with the large number of available drugs currently under investigation is likely to offer additional rational therapeutic approaches for cancer." (PMID 35006426, 2021). "DARPP‐32 is phosphorylated by PKA or Cdk5 to alter its inhibitory activity; Cdk5 is involved in neuronal maturation but is also implicated in cancer and neurodegenerative disorders." (PMID 33991172, 2021). "The allele frequencies of mutations on CDK5 are low in various cancer samples, but some mutations located in key domains of CDK5 likely influence its structure and PTMs, which contribute to tumorigenesis." (PMID 35006426, 2021). "There has been growing and important evidence showing that Cdk5 is also linked to a variety of cancers including prostate cancer, medullary thyroid carcinoma, liver cancer, lung cancer, and CRC." (PMID 33488528, 2020). "In cancer, high Cdk5 protein and mRNA expression is associated with clinicopathological features associated with a poor prognosis or adverse survival in a number of tumour types." (PMID 32352232, 2020). "Studies have assessed the expression of Cdk5 and its association with survival in cancer; however, this has been in tumour types other than breast." (PMID 32352232, 2020). "Cdk5 has been shown to play an important role in numerous pathways linked with cancer, with low and high expression associated with survival and or clinicopathological criteria dependent upon tumour type." (PMID 32352232, 2020). "Various researches have revealed that overexpression of CDK5 was associated with cancer progression and worse prognosis, and inhibition of CDK5 activity was determined to suppress growth in numerous cancers." (PMID 31496920, 2019). "Cyclin-dependent kinase 5 (CDK5) seems to be of importance since high levels of CDK5 were found in different cancers associated with high USF2 expression." (PMID 31013770, 2019). "Autophagy activation insures and protects cancer cells, and this process in known as adaptive autophagy, which is directly associated with CDK5." (PMID 31698798, 2019). "Recently, it has been revealed that loss of Cdk5 in cancer increased the production of mitochondrial ROS." (PMID 30911317, 2019). "Cdk5 is reactivated in several metastatic human cancers, including lung, and is associated with poor prognosis." (PMID 30452490, 2018). "Loss of Cdk5 activity in many cancers results in persistent overexpression of the interferon regulatory factors IRF2 and IRF2BP2, two PD-L1 transcriptional repressors that negatively regulate PD-L1 expression in tumor cells." (PMID 30687086, 2018). "CDK5 has been previously implicated in a number of cancers, including those of the pancreas, thyroid, prostate, breast, lung, liver, and most recently as a tumor promoter in CRC." (PMID 29435174, 2018).
cancer (continued). "CDK5 has recently been implicated in diseases, including the development and progression of cancer and neurodegenerative diseases." (PMID 28077789, 2017). "CDK5 emerges as an interesting candidate since its activity has been recently linked to the metastatic process in some cancers, possibility by reducing the activity of the actin regulator protein, caldesmon." (PMID 28530703, 2017). "Here we pin down the in vivo impact of endothelial Cdk5 inhibition in angiogenesis and elucidate the underlying mechanism in order to judge the potential of Cdk5 as a novel anti-angiogenic and anti-cancer target." (PMID 26755662, 2016). "Because the neuronal migration during the nervous system development and cancer cell migration and metastasis shared quite similar cellular and molecular mechanisms, several studies have linked CDK5 to cancer." (PMID 26146988, 2015). "The neuronal kinase CDK5, which functions in migration, was recently reported to be activated in human cancers and implicated in promoting metastasis." (PMID 26690371, 2015). "Although, recently, the awareness about extra-neuronal functions of Cdk5 has grown and Cdk5 was for example associated with cancer, inflammation, or metabolism, our knowledge about Cdk5 in the periphery is still insufficient." (PMID 26327394, 2015). "This elevated expression strongly correlates with cancer progression, lymph node metastasis, and poor prognosis; for instance, in bladder cancer, high Cdk5/p35 levels are associated with higher tumor grade and poor survival by promoting both proliferation and migration." (PMID 41369365, 2025). "Overactivation of CDK5 is associated with the initiation and progression of cancer." (PMID 37887415, 2023). "Cyclin-dependent kinase 5 (CDK5) has been increasingly implicated in cancer progression." (PMID 37511490, 2023). "Moreover, CDK5 was reported to be implicated in the migration and invasion of cancer cells, especially in CRC cells, reinforcing our results on the impact of TP5 on the CRC cell migration." (PMID 37511490, 2023). "In addition, CDK5 dysregulation has been associated with neurodegenerative disorders but its contribution to cancer has been, until recently, overlooked mostly because of the absence of any mutation in tumors." (PMID 36358803, 2022). "Several studies have implicated CDK5 in regulating migration and invasiveness of cancer cells, but the outcome (stimulation versus inhibition of migration) as well as the molecular mechanism remains unclear." (PMID 31910742, 2020). "In cancer, Cdk5 participates in numerous pathways associated with tumour progression." (PMID 32352232, 2020). "Through the depletion of PD-L1, CDK5 deficiency can promote CD4+ T-cell-mediated cancer cell death." (PMID 33396266, 2020). "In addition, these cancers are also associated with high expression and activity levels of cyclin-dependent kinase-5 (CDK5))." (PMID 31013770, 2019). "Increasing evidence also indicates that Cdk5 may contribute to malignant progression of some types of cancers; however, the underlying mechanism remains elusive." (PMID 31548578, 2019). "In light of its potent and wide-ranging biological activities and diverse intracellular substrates, CDK5 must be tightly regulated, and aberrant CDK5 activation is implicated in neurodegenerative diseases and cancer, and various disease processes in mouse models." (PMID 29535807, 2018). "Next, we investigated whether CDK5 mutation could possibly be contributing to its activity in CRC so we examined the mutational frequency of CDK5 in all TCGA cancers." (PMID 29435174, 2018). "Various studies have since implicated CDK5 in cell migration as it governs cancer metastasis." (PMID 28077789, 2017). "Cdk5 is generally dysregulated in various types of cancer and is linked with cancerous characteristics and prognoses, making it a novel biomarker and promising therapeutic target in cancer treatment." (PMID 28288624, 2017).
cancer (continued). "CDK5, p35 and p25 are expressed in other tissues besides brain and have been implicated in various forms of neoplasms, including thyroid, pancreatic, pituitary, breast, prostate, and lung cancers." (PMID 25900242, 2015). "Moreover, in cancer cells, CDK5, ERBB2/ERBB3, and beta-catenin have been linked through another member of the beta-catenin network—the androgen receptor (AR)." (PMID 26509276, 2015). "In addition, our data also indicate that the formation of Cdk5/p35 complex is sensitive to drug treatments and causes apoptosis in cancer cells." (PMID 23304206, 2012). "All these observations enhance the relevance of the results presented here: the characterization of how Pho85 controls the G1/S repressor Whi7 could help to better understand the mechanism underlying cell cycle activation by Cdk5 in neurodegenerative disorders or in cancer." (PMID 38233717, 2024). "However, various studies have shown that CDK5 is involved in tumorigenesis and the progression of a wide variety of cancers and may also be associated with drug resistance." (PMID 35715750, 2022). "However, CDK5 mediated movement could also be an underlying driver of cancer metastasis and could be targeted in treatments to halt cancer metastasis." (PMID 28077789, 2017). "Since Cdk5-mediated regulation of p27kip1 is associated with several cancers, a Cdk5-p27kip1 pathway might determine an amoeboid morphology through the regulation of cofilin in cancer." (PMID 22605996, 2012). "Therefore, Cdk5/p35 might be considered as a potential diagnostic and therapeutic target for cancers in the near future." (PMID 23304206, 2012). "Cyclin-dependent kinase 5 (CDK5) is a critical regulator of neuronal development and function, whose hyperactivation exacerbates neurodegenerative disorders and certain cancers." (PMID 42312138, 2026). "Beyond shaping the physical microenvironment, Cdk5 is a critical modulator of the interaction between cancer cells and the immune system." (PMID 41369365, 2025). "This review explores the functional duality of Cdk5 by comparing its constructive role in neurodevelopment with its repurposed oncogenic function in cancer." (PMID 41369365, 2025). "Beyond promoting cell proliferation, Cdk5 plays a direct role in the physical dissemination of cancer cells." (PMID 41369365, 2025). "In contrast to its constructive roles in neurodevelopment, Cdk5 is frequently repurposed in cancer, where it promotes a wide array of malignant phenotypes." (PMID 41369365, 2025). "The role of Cdk5 in other key TME components, such as Cancer-Associated Fibroblasts (CAFs), remains less understood but represents a promising area for future research." (PMID 41369365, 2025). "This starkly opposing regulation of PD-L1 in different cancer types illustrates the profound complexity of Cdk5 signaling and underscores the need for context-specific investigation." (PMID 41369365, 2025). "Once cancer cells acquire migratory potential, Cdk5 directly modulates cell adhesion and cytoskeletal dynamics." (PMID 41369365, 2025). "This review will first explore the integrative roles of Cdk5 in normal neurodevelopment and then examine how these functions are repurposed in cancer to drive disease progression." (PMID 41369365, 2025). "By phosphorylating a diverse set of substrates, Cdk5 drives cancer cell proliferation, enhances survival and therapeutic resistance, promotes invasion and metastasis, and actively shapes the tumor microenvironment." (PMID 41369365, 2025). "Understanding this repurposing of cellular machinery provides a strong conceptual framework for Cdk5’s dual roles and reinforces its significance as a therapeutic target in cancer." (PMID 41369365, 2025). "Collectively, by targeting these distinct cellular components—focal adhesions, the cytoskeleton, and signaling cascades—Cdk5 comprehensively regulates the molecular machinery required for cancer cell invasion and migration." (PMID 41369365, 2025).
cancer (continued). "Cdk5 can act at the earliest stages of this process by regulating the ‘migration–proliferation dichotomy,’ a critical decision point for cancer cells." (PMID 41369365, 2025). "In contrast to its role in promoting cell cycle exit in neural development, Cdk5 functions as a potent driver of proliferation in many cancers." (PMID 41369365, 2025). "Emerging evidence reveals that Cdk5 is a key player in this interplay, acting not only within cancer cells but also on the surrounding stromal components to shape a pro-tumorigenic niche." (PMID 41369365, 2025). "CDK5, in addition to its role in cancer cells, is also expressed in immune cells and regulates T-cell activation." (PMID 41561738, 2025). "As discussed in the context of cancer, Cdk5 phosphorylates STAT3 and the androgen receptor (AR), enhancing their pro-proliferative transcriptional programs." (PMID 41369365, 2025). "CDK5, a proline-directed serine/threonine kinase, is aberrantly active in multiple cancer types and has emerged as a key regulator of PD-L1 expression." (PMID 41561738, 2025). "In cancer, however, many of these same checkpoints are dysregulated, leading to chronic, aberrant Cdk5 activation that drives malignant traits." (PMID 41369365, 2025). "By destabilizing PD-L1, Cdk5 prevents cancer cells from inactivating T cells, thus promoting immune surveillance." (PMID 41369365, 2025). "The in vitro and in vivo experiments demonstrated that LIMK1 cooperates with Cyclin‐dependent kinase 5 (CDK5) to promote cancer metastasis in a phosphorylation‐dependent manner." (PMID 40476449, 2025). "One explanation is that dinaciclib targets CDK5, a known regulator of cancer cell motility, which in our cell lines override PIK-75 effects, even though PI3Ks play key roles in regulating cell motility." (PMID 38254859, 2024). "Cyclin-dependent kinase 5 (CDK5) is involved in chemotherapy resistance in different types of cancer." (PMID 38474332, 2024). "Accordingly, it has been demonstrated that in HeLa cells overexpressing cyclin I, the activation of CDK5 by cyclin I confers cancer cell resistance to CP, while knockdown of CDK5 with siRNA significantly increases the sensitivity to CP." (PMID 38474332, 2024). "In this study, molecular docking was performed on 12 different molecules identified by GC/MS and proteins in cancer cells, such as cyclin-dependent kinase 5, cytochrome P450 aromatase, erythroid spectrin, and topoisomerase." (PMID 36903287, 2023). "Overall, compared with normal tissues, the expression of CDK4 and CDK5 are higher in 18 out of 24 or 75% of the cancers listed." (PMID 37311884, 2023). "Evidence suggests that increased expression of Cyclin-dependent kinase 5 (CDK5) contributes to cancer progression, making it a promising target for treatment." (PMID 37511490, 2023). "In this respect, CDK5 hyperactivation in cancer mimics neurodegenerative diseases where CDK5 deregulation via p25 is toxic." (PMID 37993880, 2023). "Recently, accumulating evidence revealed that CDK5 has oncogenic functions in a variety of cancers, including colon, lung, breast, brain, pancreatic, and melanoma cancers." (PMID 37990321, 2023). "Further optimization of a CDK5/p35 kinase inhibitor that is both potent and selective would thus treat cancer through both NK-dependent and NK-independent mechanisms, potentially improving outcomes compared with using just either strategy alone." (PMID 37377891, 2023). "Our data revealed a kinase-independent function of CDK5 in regulating IFN-β in A549 cells during VSV infection, this finding also suggests a potential therapy for cancers by targeting the protein level of CDK5." (PMID 37332205, 2023). "In PCa cells, cdk5 promotes cell growth in an androgen receptor- independent way and stimulate cancer progression." (PMID 37000265, 2023). "Cdk5 (3ig7) is a viable therapeutic target receptor for developing novel cancer medicines due to its extensive protumorigenic activity." (PMID 36903287, 2023).
cancer (continued). "Equally importantly, it is critical to analyze the subcellular localization of CDK5 activators in each cancer." (PMID 37993880, 2023). "This review focuses on the molecular mechanisms by which CDK5 recruits diverse tissue-specific substrates to elicit distinct phenotypes in sixteen different human cancers." (PMID 37993880, 2023). "The growing evidence of CDK5’s role in cancer progression has made it a potential target in oncology, particularly in the treatment of metastatic colorectal cancer, where genotoxic agents are often used as a first-line therapy." (PMID 37511490, 2023). "While acting as a bonafide oncogene, CDK5 also activates a few cancer-suppressive pathways in some cancers, presumably due to the mislocalization of nuclear substrates in the cytoplasm." (PMID 37993880, 2023). "While CDK5 and/or p35 upregulation in neurons promotes healthy neuronal functions, their upregulation in cancer promotes highly aggressive phenotypes." (PMID 37993880, 2023). "Conversely, increasing evidence suggests a proapoptotic role for CDK5 in some human cell types and a role in suppressing tumorigenesis in several human cancers." (PMID 37990321, 2023). "We now approach CDK5 and cancer from an immunotherapy angle as well, by which inhibition of the CDK5/p35 would enhance NK-cell antitumor cytotoxicity and inhibit tumor microenvironmental TGFβ-mediated NK-cell dysfunction." (PMID 37377891, 2023). "This research endeavors to contribute to the ongoing quest for innovative anti-cancer therapies, with a particular focus on CDK5 inhibition." (PMID 37887415, 2023). "Most importantly, analysis of CDK5’s substrates and pathways in sixteen different cancers suggests that CDK5’s behavior as an oncogene or an anti-oncogene depends upon its subcellular localization." (PMID 37993880, 2023). "Up-to-date research established an evident correlation between CDK5 aberrant activation and/or overexpression and tumorigenesis, mutagenesis dissemination, and cancer disease progression in a variety of cancers." (PMID 37887415, 2023). "It is now obvious that CDK5 is dysregulated in multiple cancer types, and it needs to receive more attention." (PMID 36358803, 2022). "Cyclin-dependent kinase 5 (CDK5) is a member of the protein kinase family that has been shown to play a role in cancer development and the TME." (PMID 35309935, 2022). "In fact, an increased expression of Cdk5 have been reported in pancreatic, colorectal, prostate, breast and ovarian cancers, glioblastoma multiforme and multiple myeloma." (PMID 36142566, 2022). "Although its altered regulation mainly leads to neurodegeneration, Cdk5 is ubiquitous, and its aberrant expression has been observed in multiple types of solid and hematological malignancies." (PMID 36142566, 2022). "Cdk5 regulates numerous functions in the nervous system, is involved in neurodegenerative disease, and affects cancer progression." (PMID 35421092, 2022). "Exploiting the vascularized microfluidic MVN chips, the role of the Cdk5/Tln1/FAKS732 axis in each step of cancer extravasation was studied: vascular adhesion, trans-endothelial migration, and early invasion." (PMID 35158914, 2022). "By contrast, mitosis-independent phosphorylation at S75 occurs in Y79 retinoblastoma cells and some cancer cell lines, and is mediated by Cdk5/p35 kinase." (PMID 35216357, 2022). "Some preclinical studies using CRISPR/Cas9 technology have highlighted the importance of some genes, including SLFN11, APE1, RSF1, and CDK5, in cancer drug resistance." (PMID 35715750, 2022). "The Cdk5 inhibitor roscovitine has shown promising results in several phase I and phase II cancer clinical trials both as a monotherapy and as a combination therapy." (PMID 35383146, 2022). "Anti‐Chi3L1 antibody significantly decreased the expression of cancer growth and migration‐associated proteins, such as PCNA, cyclin D1, cyclin E, Cdk2, Cdk4, Cdk5, MMP2 and MMP9 in A549 lung metastasis model tissues." (PMID 34861103, 2022).